BAX (BCL2 associated X, apoptosis regulator)
Diseases named in the same sentence as BAX in open-access papers (continued):
Sharing a sentence is not in itself a finding about the gene and the disease.
cancer (continued). "In our study, upon treatment with LP 1010 CFU/mL the protein level of Bcl-2 was decreased, whereas BAX levels were increased in all three cancer cell lines, thus revealing one molecular mechanism for the apoptosis of the tested cancer cells." (PMID 38258008, 2024). "Real-time PCR and immunohistochemistry (IHC) were further performed to examine the BAX expression in cancer cells and tissues." (PMID 39074253, 2024). "CTSG enters cancer cells through cell surface protein RAGE and cleaves 14-3-3ε, which leads to BAX mitochondrial translocation and triggers apoptosis of cancer cells." (PMID 38194275, 2024). "The CPTAC data also showed that BAX protein expression was higher in some other cancer tissues than in adjacent normal tissues, such as PAAD, OV, KIRC and BRCA." (PMID 39074253, 2024). "Research shows that the balance between anti-apoptotic and pro-apoptotic proteins, such as BCL2 and BAX, works well for the proliferation of cancer cells." (PMID 39605919, 2024). "The study highlights the importance of investigating the immune response of the BAX gene to tumors in pan-cancer to improve the understanding of the tumor microenvironment." (PMID 39074253, 2024). "Mechanistically, RVS downregulates the ATF4/Chop/BCL-2/BAX signaling pathway, contributing to anti-aging and anti-cancer effects and synergistic effects with agents like prednisolone enhance apoptosis through BAX and BCL-2 modulation." (PMID 39769099, 2024). "The mechanisms by which D-limonene and α-pinene, the key components of CPEOs, upregulate BAX and induce apoptosis in cancer cells have been confirmed in T-cell tumor, AGS, HepG2, and MCF-7 cells." (PMID 39857347, 2024). "Compared with normal tissues, the result revealed that the expression level of BAX was highly expressed in eighteen of the twenty-one cancer types for which complete data were available." (PMID 39074253, 2024). "A study found that CLA extracted from L. plantarum exhibited anti-cancer activity in mammalian breast cancer cell lines by suppressing the NF- κB pathway and then by upregulation of the BAX gene leading to an apoptotic pathway." (PMID 39372197, 2024). "Together, these results show that BAX–BAK structures do not only occur in immortalized cancer cells but are a physiological phenomenon during apoptosis in human cells and that the rings composed of endogenous BAX and BAK are delineating a pore in the MOM." (PMID 38503846, 2024). "At present, the prognosis and immune infiltration of BAX is largely unexplored and lacks systemic assessment among 33 human cancers." (PMID 39074253, 2024). "The development of cancer mostly relies on the misbalance between pro-apoptotic proteins (e.g., BAX) and anti-apoptotic proteins (e.g., BCL2)." (PMID 39062071, 2024). "We used the TIMER2.0 tool to create heat maps and found a strong positive correlation between BAX and the first five genes in most cancer types." (PMID 39074253, 2024). "Concurrently, hesperidin treatment led to a substantial increase in BAX mRNA expression, indicating an enhancement in cell death and a favorable outcome in combating cancer." (PMID 38435153, 2024).
cancer (continued). "Cancer cells often evade apoptosis by overexpressing the antiapoptotic inhibitor BAX; however, small-molecule activators of BAX have been shown to overcome this effect and inhibit cancer growth in animal models." (PMID 38921586, 2024). "We conducted the gene expression analysis and survival analysis of BAX in 33 types of cancer via Gene Expression Profiling Interactive Analysis (GEPIA) database." (PMID 39074253, 2024). "Current research on BAX protein focuses on its ability to inhibit cancer cell proliferation by promoting apoptosis of cancer cells." (PMID 39529669, 2024). "It suppresses miR‐32 expression, downregulates BCL‐2 expression, upregulates BAX, Bim, and cytosolic CytC expression, promotes cleavage of caspase‐3 and ‐9 proteins, halts the cancer proliferation, and stimulates apoptosis." (PMID 38726411, 2024). "We sought to find relationships between the mRNA expression of BAX and drug sensitivity by using Genomics of Drug Sensitivity in Cancer (GDSC) and Cancer Therapeutics Response Portal (CTRP) independent drug response datasets." (PMID 39074253, 2024). "In order to further verify the expression of BAX in tumor tissues, we downloaded immunohistochemical staining of these cancers." (PMID 39074253, 2024). "Herein, we performed a comprehensive analysis to explore that BAX gene plays an important role in the development of many cancers." (PMID 39074253, 2024). "In order to investigate the anti-cancer effect of HCFs on HepG2 and HC cells in addition to gene expression studies, the expression levels of BAX and BCL-2 proteins were also measured and BAX / BCL-2 ratio was determined." (PMID 38372909, 2024). "In terms of more clinical relevance, we indicated that the expression of BAX has significant difference in cancer stages." (PMID 39074253, 2024). "Understanding the balance between Bcl-2 and BAX expression is crucial for developing targeted cancer therapies that can restore normal apoptotic regulation and induce cancer cell death." (PMID 37185746, 2023). "Cell viability assays revealed that the removal of NINJ1 did not have marked impact on APR-246 induced killing but significantly reduced the release of LDH in both the parental cancer cells and their BAX/BAK double knockout derivatives." (PMID 36739334, 2023). "Here we show that, surprisingly, cancer cell lines express cytosolic inactive BAX dimers and/or monomers." (PMID 38104127, 2023). "Our findings support the notion that the formation of the inactive BAX dimer is a mechanism adopted by cancer cells to further suppress BAX activation and gain a survival advantage." (PMID 38104127, 2023). "BAX and Bcl‐2 genes were studied with qRT‐PCR to investigate the different ways that cancer cells undergo apoptosis." (PMID 37285457, 2023). "SFN-mediated HDAC inhibition has been reported to enhance histone acetylation and derepress p21 and BAX gene expression, resulting in the induction of cell cycle arrest/apoptosis in several types of cancer cells." (PMID 36899823, 2023). "In summary, our findings here provide insights into the regulation of BAX through its cytosolic conformation and advance our understanding of mechanisms of resistance to BAX-mediated apoptosis in cancer cells." (PMID 38104127, 2023). "A latest study found that mitochondrial HK2 prevents mitochondrial translocation of BAD, BAX proteins and activation of caspase-3, thereby alleviating drug-induced pyroptosis of cancer cells." (PMID 38076208, 2023). "In another study, the authors reported that the expression of BAX in cancer tissues is significantly higher than in healthy tissues." (PMID 37644520, 2023).
cancer (continued). "Mechanistic studies have shown the modulation of apoptosis related proteins such as BCL-2 and BAX with varying expression of IL-8 suggesting the involvement of Hsp60-IL-8 axis in apoptosis resistance in cancer." (PMID 37232720, 2023). "qRT-PCR of the following genes and main regulated processes: AKT and KI67 (cancer proliferation) as well as BAX and BCL2 (apoptosis) was performed." (PMID 37048115, 2023). "Here, the authors describe cytosolic BAX dimers, which in cancer cells inhibit BAX activation and they develop a strategy to modulate BAX dimers to potentiate BAX-mediated apoptosis." (PMID 38104127, 2023). "Here, our systematic analysis of cytosolic fractions of various hematological and solid tumor cell lines supports the existence of cytosolic inactive BAX dimers in several cancer cells." (PMID 38104127, 2023). "Top-scoring regulators of apoptosis, CASP8, BAX, and MCL1, indicated the mode of cell death induced by IFN-γ, and support the association of CASP8 mutations with immune evasion in TCGA pan-cancer analyses." (PMID 36669486, 2023). "For instance, regulation of pro-apoptotic genes BAX, caspase-3 and caspase-9 is a major event in cancer development and progression." (PMID 37958747, 2023). "The results showed that the expression of apoptosis-related genes in cancer cells changed after treatment with saponins—BAX mRNA increased, and BCL-XL mRNA decreased." (PMID 37447047, 2023). "Considering the role of the cytosolic inactive BAX dimer in resistance to apoptosis in cancer cells, we sought to identify a small molecule that modulates cytosolic BAX dimer." (PMID 38104127, 2023). "Conversely, reduced expression of BAX in cancer cells can also contribute to resistance to apoptosis." (PMID 37185746, 2023). "This provides the means for cancer cells to block the activation of pro-apoptotic effectors BAX/BAK and apoptosis induction." (PMID 38104127, 2023). "Hsa-miR-298 has also been defined as oncomiRNA in several cancers, thanks to its ability to downregulate proapoptotic proteins such as BAX and PTEN." (PMID 35039944, 2022). "The ratio of BCL-2 to BAX is a factor that determines the relative sensitivity or resistance of cancer cells to apoptotic impulses and therapeutic drugs." (PMID 35328794, 2022). "Overwhelming evidence has shown that antiapoptotic BCL-2 is activated while proapoptic BAK and BAX are inhibited in many cancers, affecting the resistance of cancer cells to drugs." (PMID 36411463, 2022). "As another concern, many traditional medicines suppress cancer cells primarily depending on the BCL-2/BAX mechanism." (PMID 36230771, 2022). "As expected, a stronger BAX signal was detected in the BRCA1 knock-down cancer cells upon IR irradiation, and the percentage of BAX-positive cells increased to 61.2%." (PMID 35517499, 2022). "The development of small molecules that directly activate BAX represents a major advance in our ability to selectively promote apoptosis in cancer cells." (PMID 35256598, 2022). "In this regard, our results open new avenues for the use of BID activation as a strategy to kill cancer cells that have become insensitive to BAX and BAK." (PMID 34931711, 2022). "Such pathologies accumulate and lead to somatic mutations, including reading frame alterations in genes, such as APC, TGFBR2 or BAX, which results in an accelerated process of polyp-to-cancer transformation in large polyps." (PMID 36553592, 2022). "Numerous studies have revealed that curcumin triggers apoptosis through BAX/BCL-2 mediated pathway in cancer cells." (PMID 35566271, 2022). "This norbornene-containing compound has the capacity to antagonize muscarinergic receptors, which are frequently expressed in cancer cells, responsible for cancer progression and the promotion of the proapoptotic factor BAX." (PMID 36558915, 2022).
cancer (continued). "BAX is a key protein in the process of cancer apoptosis, which can promote the apoptosis of cancer cells." (PMID 35432564, 2022). "Connections between SRSF6 and alternative splicing of the cell death protein BAX complement multiple studies that correlate altered SRSF6 expression levels with cancer progression." (PMID 36409059, 2022). "The expression of miR-365 was found to be high in pancreatic cancer cells; it directly targets the pro-apoptotic regulator BAX and thus prevents cancer cell death by blocking the release of AIF and cytochrome c." (PMID 36013278, 2022). "If the cells were treated with dobutamine beforehand, weaker BAX signals were observed in the IR-irradiated control and BRCA1 knock-down A2780 cells, and 13.7 and 14.5% cancer cells were BAX positive, respectively." (PMID 35517499, 2022). "The most common pathway used by cancer cells to evade apoptosis is based on the upregulation of antiapoptotic BCL-2 proteins and the loss of BAX/BAK proteins; indeed, BCL-2 gene overexpression is present in over half of all cancers." (PMID 36291779, 2022). "Precisely, nisin causes an imbalance in the expression of BAX/BCL-2 expression ratio and a higher expression of the pro-apoptotic proteins at the messenger ribonucleic acid (mRNA) and protein level of the cancer cells." (PMID 36230679, 2022). "In pancreatic cancers, EGR1 binds to the Bax gene promoter to activate BAX expression, which subsequently leads to cancer cell apoptosis." (PMID 35563324, 2022). "It contributes to the transcriptional activation of several genes, including BCL2-associated X(BAX) and GADD45A, which in turn stop cancer cell proliferation and delete or diminish cancer cell tumorigenic potential." (PMID 35631261, 2022). "Semi-quantitative immunofluorescence staining also concurs with these data, wherein a strong BAX expression was observed in the epithelial tissues of low-grade cancer samples." (PMID 36013602, 2022). "The BAX complexes formed are consistent with the finding that BCL-XL is a key player in the apoptotic resistance of these cancer cell lines as immunoprecipitated BAX had more interactions with BCL-XL." (PMID 35256598, 2022). "Frequently, cancer cells upregulate anti-apoptotic BCL-2 family members to inhibit pro-apoptotic BCL-2 members BAX, BAK, and BH3-only proteins, thus blocking apoptosis." (PMID 35256598, 2022). "It has been shown that TZB initiates the apoptosis signaling in cancer cells by suppressing the anti-apoptotic family, Bcl-2 members, which subsequently induces up-regulation of BAX, apoptosis inducer." (PMID 34669701, 2021). "Compound 42 presented proapoptotic effects in cancer cell lines, inducing cell cycle arrest at the G0/G1 phase, increased p21 and BAX, and decreased BCL-2 antiapoptotic proteins." (PMID 33802144, 2021). "In this study, we investigate how an intracellular signalling network (STAT1, STAT3, Bcl-2 and BAX) regulates important cellular states, either anti-apoptosis or apoptosis of cancer cells." (PMID 34631119, 2021). "have found that tumor necrosis factor α+ cycloheximide and navitoclax-induced cancer cell pyroptosis through a BAK/BAX-caspase-3-GSDME signaling pathway." (PMID 34484243, 2021). "Overall, these results suggest that DUSP16 promotes resistance to chemotherapy drugs in cancer cells through prevention of BAX accumulation in the mitochondria and the activation of mitochondria cell death pathway, thereby suppressing apoptosis." (PMID 33863904, 2021).
cancer (continued). "The gene expression ratio of BAX/BCL-2 indicated the induction of mitochondrial apoptosis in two cancer cell lines (SNB-19 and MDA-MB-231)." (PMID 33807874, 2021). "On the other hand, as the ATV injection period is increased (τA = 0 → 1 → 4 → 10), the Bcl-2 level is increased and BAX activities are reduced, reducing the probability of apoptotic death of cancer cells through decreases in persistence of apoptosis." (PMID 34669701, 2021). "In this case, Lactobacillus EPSs were found to induce apoptosis in CRC in vitro through the increased expression of Caspase 3, Caspase 9, and BAX and decreased levels of Bcl-2, which led to a decline in cancer cell survival." (PMID 34068653, 2021). "Our study was reliable with the tissue-specific association of BAX -248 G>A and BCL2 -938 C>A polymorphisms in the context of the global cancer prognosis." (PMID 33906310, 2021). "So far, promoter polymorphism of BAX -248 G>A and BCL2 -938 C>A are two of the most studied polymorphisms reported being associated with the increased risk of cancers." (PMID 33906310, 2021). "Taking into account that there are currently different SMAC and BAX mimetics for the treatment of cancer at different stages of development, our model would support the idea that BAX mimetics would be more effective than SMAC mimetics." (PMID 33558564, 2021). "Apoptotic pathways in cancer cells are disrupted by downregulation of BAX and BAK or upregulation of anti-apoptotic B-cell lymphoma-2 (BCL-2) proteins." (PMID 34830916, 2021). "Among members of the basic circuitry for evasion of the apoptotic process in cancer, BAX and BCL-2 are tightly coregulated, inhibiting mitochondrial function." (PMID 33531986, 2021). "We investigated the sensitivity of densities of cancer cells (C), IL-6 (L), NF-κB (F), Bcl-2 (B) and BAX (X) to these parameters at several time points." (PMID 34669701, 2021). "Both JNK and p38 have been shown to promote BAX translocation to mitochondria to mediate apoptosis in response to drug treatment in cancer cells." (PMID 33863904, 2021). "Bcl-2 is a well-recognized gate-keeper, preventing the cellular death of cancer cells by inhibiting BAX." (PMID 34631119, 2021). "PCC1 was shown to decrease the level of BCL-2 but increase expression of the regulator BAX and activities of caspases 3 and 9 in cultured cancer cells, thus potentially generating anticancer effects through induction of apoptosis." (PMID 34873338, 2021). "The nanoparticles efficiently promoted cancer cell apoptosis by regulating the B cell CLL/lymphoma 2 (BCL2), BCL2-associated X protein BAX, cleaved caspase-3, matrix metalloproteinase (MMP)-2, and MMP-9 pathways." (PMID 33925605, 2021).